CSF1R (colony stimulating factor 1 receptor)
Diseases named in the same sentence as CSF1R in open-access papers (continued):
Sharing a sentence is not in itself a finding about the gene and the disease.
tumor (continued). "Meanwhile, the autophosphorylation of the CSF-1R signaling pathway is effectively inhibited by PLX3397, resulting in the inhibition of the downstream signaling molecules PI3K, AKT, ERK, and RAF, which affect tumor cell function." (PMID 38303927, 2024). "In contrast, tumour tissue‐enriched C5‐TREM2‐Mφ and C8‐MT1H‐Mφ macrophages displayed a more anti‐inflammatory phenotype, with high expression of genes such as CD163, MARCO, and CSF1R, indicative of an M2‐like phenotype." (PMID 37994257, 2024). "Finally, the depletion of macrophages with a CSF1R monoclonal antibody improved gemcitabine antitumour activity, particularly for SEMA3A expressing tumours." (PMID 38670629, 2024). "Many studies observed the involvement of CSF-1R signaling in the promotion of stemness and chemoresistance mechanisms, making CSF-1R in tumor cells a negative predictor of outcome." (PMID 38254773, 2024). "Immunofluorescence confirmed that IL-33 induced an accumulation of M2 macrophages, whereas CD163 was absent in tumor tissues of 615-line mice treated with anti-CSF1R." (PMID 38238529, 2024). "Following our observations of epitope spreading and modulation of the M1/M2 phenotype post-CSF1R blockade, we asked whether the combination of anti-CSF1R therapy with an adeno-TWIST1 vaccine would result in improved tumor control." (PMID 37505292, 2023). "Interestingly, monoclonal antibodies and small-molecule inhibitors targeting CSF1R have been reported to result in a decreased number of TAMs and an increased ratio of CD8+/CD4+ T cells in the tumor." (PMID 38035101, 2023). "Importantly, a lung cancer mouse model demonstrated that a CSF1R inhibitor reduces the number of NK cells in the TME and enhances tumour metastasis." (PMID 37313600, 2023). "The anti-tumor effectiveness of CD8+T cells has been demonstrated to be improved and the survival duration of mice with colon cancer lengthened in other studies using a combination of PLX3397(CSF-1R inhibitor), oncogenic virus, and anti-PD-1 antibody." (PMID 37138860, 2023). "Consistent with the immune surveillance function of macrophages, the tumor xenografts in NSG mice bearing CT26 cells were found to grow faster in presence of CSF1R antibody than that in absence of CSF1R antibody." (PMID 37607946, 2023). "In preclinical models performed by our groups and others, elimination of TAMs by CSF1R blockade alone did not result in substantial inhibition of tumor growth." (PMID 37964379, 2023). "In human and mouse lung cancer, PLX3397, a CSF1R inhibitor, reversed the long-term interaction between CD8 T cells and TAMs, thereby depleting TAM and inhibiting the migration and infiltration of T cells at the tumor site." (PMID 37313405, 2023). "Macrophages and colony-stimulating factor 1 receptor (CSF1R) dependent inflammatory cells are components of TSGCT, which may be controlled by tumor cells and result in bone resorption." (PMID 37923984, 2023). "The results showed that TAM had a significantly positive CSF1R phenotype, while macrophages in the spleen of tumor-bearing mice had a negative CSF1R phenotype." (PMID 36969873, 2023). "Many inhibitors, such as inhibitors of ANG2 (Trebananib), CCL2/CCR2 (Carlumab and PF-04136309), CCL5/CCR5 (Leronlimab, Maraviroc, and Maraviroc), CSF-1/CSF-1R (Emactuzumab and Pexidartinib), and VEGF have been shown to inhibit macrophage recruitment for tumor growth." (PMID 37211559, 2023). "When we evaluated dosing implications of anti-CSF1R in the parental, less immunogenic cell line, YUMM1.7 we did not see any tumor regression nor difference in survival between lower and higher anti-CSF1R dosing." (PMID 37964379, 2023). "In the H22 tumor‐bearing mouse model, the CSF1/CSF1R inhibitor PLX3397 diminishes macrophage recruitment and M2 polarization and cooperates with immunotherapy by reshaping the tumor immune microenvironment and enhancing infiltration of CD8+T cells and mature DC cells." (PMID 38098217, 2023).
tumor (continued). "The association of the macrophage population abundance with the disease prognosis dramatically depends on the tumor subtypes, so targeting the CSF1/CSF1R pathway may vary greatly depending on the tumor subtypes." (PMID 37279073, 2023). "We found that anti-CSF1R Ab treatment reduced tumor growth and tumor weight in TPO-treated mice but not in mice in the control group." (PMID 37064877, 2023). "In our experiment, CSF1R inhibitors as monotherapy showed that a tumor growth inhibition but not tumor volume reduction within 15 DPT." (PMID 36969873, 2023). "In addition, CSF-1 induces MDSC tumor invasion and combines the treatment of anti-CTLA-4 with CSF-1/CSF-1R to inhibit MDSC signaling." (PMID 37892995, 2023). "Furthermore, it has been reported that the microglia-GBM cells’ crosstalk modulates tumor infiltration by the activation of epidermal growth factor receptor (EGFR) and colony stimulating factor 1 receptor (CSF-1R) signaling." (PMID 37108208, 2023). "This suggests that CSF1R-targeted inhibitors are more suitable for regulating the tumor immune environment rather than acting as monotherapy." (PMID 36969873, 2023). "Targeting colony-stimulating factor 1 receptor (CSF1R) or its ligand CSF-1 could prevent myeloid cell differentiation into MDSC and impede tumor progression." (PMID 36246629, 2022). "Blocking CSF-1/CSF-1R alone increased PD-1/PD-L1 expression on TAM cells and CTLA-4 expression on CD8+ T cells, whereas combination with PD-1 or CTLA-4 antagonists led to more significant T cell infiltration and tumor regression." (PMID 35874717, 2022). "Nevertheless, the expression and prognosis of CSF-1R and its relationship with tumor immunity in COAD are not clear." (PMID 35444953, 2022). "Moreover, in a pancreatic cancer mouse model, blocking of CSF-1/CSF-1R reduced M2 macrophages within the TIME and polarized the remaining TAMs into an anti-tumor phenotype." (PMID 35874717, 2022). "In their experiment, CSF-1R inhibitor alone failed to suppress tumor growth, resulting in no overall survival advantage." (PMID 35203505, 2022). "We found that inhibiting CSF1R or VEGFR significantly reduced the number of CD11b+F4/80+ TAMs and particularly the number and percentage of M2 TAMs (F4/80+CD206+CD86−) generated from co-culture with TAb2 tumor cells." (PMID 35366939, 2022). "Previous experiments have demonstrated that inhibition of CSF-1R reduces the production of the M2 phenotype in macrophages, and tumor growth is suppressed in mice lacking CSF-1R." (PMID 36091750, 2022). "This review summarizes the immune checkpoint and other receptor-ligand interaction between macrophages and tumor cells, which plays an indispensable role in anti-tumor immunity or pro-tumor immunity, such as SIRPα-CD47, PD1-PD-L1, FcγR-Antibody-Antigen, CSF-1/CSF-1R axis." (PMID 36497444, 2022). "As expected, blockade of either CSF1R (in CAFs), or MIP2 (in CAFs), or CXCR2 (in macrophages) enhanced the IL-12/IL-10 expression ratio in the latter, which was further corroborated with enhanced cytotoxicity against tumor cells." (PMID 35315360, 2022). "CSF-1R is not mainly expressed in tumor cells and has very limited effects in directly regulating tumor malignancy in COAD." (PMID 35444953, 2022). "A previous study found that TAM depletion with a colony-stimulating factor-1 receptor (CSF-1R) inhibitor enhanced CD8+ T cell motility and infiltration into tumors, and further combination therapy with anti-PD-1 increased the contact between tumor cells and CD8+ T cells." (PMID 36555393, 2022). "Similarly, the combination of PD-1 antibody with CSF-1R inhibitor and selective CXCR2 inhibitor significantly reduce tumor growth compared with PD-1 antibody alone." (PMID 35672862, 2022). "Although CSF-1R inhibition did not regulate levels of total macrophages in the tumor microenvironment, intriguingly, it did demonstrate the capacity to normalize KD-induced changes in macrophage polarization." (PMID 36428642, 2022).
tumor (continued). "Here we have shown that CSF-1R expression had a tremendous effect on tumor growth as compared to cells that did not express CSF-1R." (PMID 36555673, 2022). "Moreover, we confirmed that CSF-1R mainly is expressed in COAD TAMs and contributes heavily to tumor immune environments." (PMID 35444953, 2022). "The proposed mechanistic model derived from our in vitro experiments is compatible with those derived from transgenic mice where genetic ablation of CSF1R in macrophages failed to attenuate tumor progression and vessel density." (PMID 35315360, 2022). "In addition, the relationship between CSF-1R in tumor microenvironment (TME) and tumor immunity was also studied." (PMID 35444953, 2022). "We then analyzed the associations between CXCL2 expression and classical macrophage phenotype markers of M0 (undifferentiated) (AIF1), M1 (anti-tumor) (IL12A, TNF, NOS2, PTGS2) and M2 (tumor-promoting) (IL10, CD163, TGFB1, CSF1R) in TCGA-LIHC cohort with Spearman’s rank correlation test." (PMID 36276119, 2022). "In contrast, anti-CSF1R or anti–PD-1 therapy did not result in any measurable effects on tumor growth in either model." (PMID 35179953, 2022). "Therefore, we aim to explore the prognostic value of CSF-1R in COAD and its relationship with tumor immunity." (PMID 35444953, 2022). "In fact, metastasized primary BC had higher tumor epithelial and stromal expressions of CSF-1 (p < 0.001 and p = 0.002, respectively) and CSF-1R (both p = 0.03) compared to non-metastatic cancers." (PMID 36294305, 2022). "Based on the negative association between CSF-1 and infiltration of CD8+ T cells, we assumed that CSF-1 is a critical factor in regulating the CSF-1R+CD11c+ MDSC cells in the TME and can thus prevent tumor elimination mediated by the trametinib/αPD-1 combination." (PMID 35292516, 2022). "Therefore, there is a negative correlation between LAL expression and expansion of CD11c+, PD-L1+, and CSF1R+ cells in patients with NSCLC, similar to that observed in the Lal–/– model and tumor-bearing mice." (PMID 35917184, 2022). "Furthermore, RNA sequencing analysis from TCGA data showed that the expression of NOS3/NOS3 positively correlated with the expression of CSF1, CSF1R, CD163, and several other tumor-promoting immune cell markers in high-grade PCa (Gleason 9)." (PMID 36209194, 2022). "Interestingly, we observed an influx of apparently round CSF-1R+, TSPO+ cells within the tumor area." (PMID 35115369, 2022). "CSF1R inhibition reduced MPE size and intrapleural tumor spread." (PMID 35315360, 2022). "The percentages of macrophages in the tumor tissues treated with all PLX formulations were lowered compared with saline and NP@Gel groups, demonstrating the TAM depletion capability of PLX by blocking CSF1R." (PMID 35387972, 2022). "Moreover, several macrophage antigens, such as CD45, CD11b, Csf1R, and F4/80, were expressed by RFP/GFP tumor hybrids, suggesting that tumor cells have preferentially fused with macrophages." (PMID 35562905, 2022). "CSF1R blockade reduced CAFs in both adenocarcinoma models, while tumor CAF infiltration was not affected in the genetic CSF1R-ablated models." (PMID 35315360, 2022). "Similarly, CSF-1R inhibition with PLX5622 in a mouse model of medulloblastoma, reduced TAMs (IBA1+ microglial cells) around 60%, which reduced tumor growth and prolonged mouse survival." (PMID 35053602, 2022). "We therefore focused on tumor-CAF-macrophage interplay and hypothesized that blockade of CSF1R/CSF1 signaling at CAFs might reverse their protective role on tumor cells." (PMID 35315360, 2022).
tumor (continued). "However, apart from decreasing TAM frequencies at tumor sites, targeting the CSF1/ CSF1R axis can also repolarize TAMs to an ‘M1-like’ phenotype." (PMID 34638388, 2021). "Intriguingly, CSF-1R-mediated macrophage depletion during the pre-malignant phase in the absence of a palpable tumor significantly reduced lung metastatic burden." (PMID 33924237, 2021). "Furthermore, in healthy and tumor-bearing aged female C57BL/6J mice (20–23 months) we have observed downregulation and internalisation of CSF-1R on monocytes/macrophages (unpublished observations)." (PMID 33441138, 2021). "In addition, combining CSF1R inhibitors with a CXCR2 antagonist blocked the infiltration of these cells and showed strong anti-tumor effect." (PMID 33842370, 2021). "Compared to the group of patients without CSF1R variant, higher CD40LG expression, a surface marker of T cells, was found in the tumor tissues of patients with CSF1R c.1085 variant." (PMID 34830445, 2021). "To study whether CD40L-mediated immune response is a potential mechanism explaining the different clinical outcome between CRCs with different CSF1R genotypes, we examined the number of CD40L+ T cells in primary CRC tumor samples." (PMID 34830445, 2021). "The low number of intratumoral macrophages observed in our study after 10 mg/kg of [89Zr]Zr-DFO-N-suc-CSF1R-mAb administration can explain the lack of specific tumor uptake of [89Zr]Zr-DFO-N-suc-CSF1R-mAb." (PMID 34976826, 2021). "CSF1R inhibition by PLX3397 reduces TAMs' tumor infiltration and their immunosuppressive phenotypes, potentiates ICI effects against PD-1 and CTLA4, and impairs tumor expansion by approximately 50%." (PMID 34476174, 2021). "This study demonstrates that [89Zr]Zr-DFO-N-suc-CSF1R-mAb is not exclusively targeting tumor macrophages but preferably distributes to other organs with high macrophage presence such as the liver and spleen, removing the antibody from circulation." (PMID 34976826, 2021). "In addition, we introduce promising biomarker candidates for practical use, including colony stimulating factor 1 receptor (CSF1R), extracellular vesicles, and cell-free, circulating tumor DNA." (PMID 34681709, 2021). "The TAMM was rich in CSF1-R, which could be exploited to capture the CSF1 secreted by tumor cells in the TME upon injection of UCNPs into tumor-bearing mice." (PMID 34683963, 2021). "These discrepancies might be attributed to the heterogenicity of different tumor species and different CSF1/CSF1R blockade agents." (PMID 34248982, 2021). "This was confirmed by ex vivo biodistribution, which also showed no specific tumor uptake of [89Zr]Zr-DFO-N-suc-CSF1R-mAb." (PMID 34976826, 2021). "Likewise, combining CSF1/CSF1R inhibitors with immunotherapies including anti-PD1 and anti-CTLA4 induces a synergistic effect and induces potent tumor regression in experimental models of PDAC." (PMID 34201127, 2021). "Tumor-bearing mice showed higher uptake of [89Zr]Zr-DFO-N-suc-CSF1R-mAb in the liver, lymphoid tissues, duodenum, and ileum, but not in the tumor than did 89Zr-labeled control at 72 h." (PMID 34976826, 2021). "Each of the myeloid cell inhibitors, including anti-Ly6G, anti-GR1, anti-Ly6C, anti-CSF1R antibodies, and CL decreased their respective mouse TIM subsets, enhancing T-BsAb-driven T cell infiltration and persistence, resulting in improved anti-tumor response." (PMID 34496935, 2021). "Small molecule CSF-1R blockades such as PLX3397 have been developed as well and have shown increased CD8+ T-cell infiltration and improved therapy response in murine models of several different tumor types." (PMID 34209703, 2021). "In GBM xenograft models, CSF-1R inhibition decreases M2 markers on TAMs but does not deplete the cell population due to tumor-secreted factors, notably GM-CSF and IFN-γ." (PMID 34976006, 2021).
tumor (continued). "Indeed, these studies suggest that the major monocyte recruiting pathways (M-CSF/CSF-1R, CCL2/CCR2, CCL3/CCR1, CCL3/CCR5, CCL5/CCR5 and CX3CL1/CX3CR1) enable tumor survival by supplying the TME with pro-tumorigenic TAMs." (PMID 34988021, 2021). "There was CSF1R-specific uptake by macrophages in the spleen and liver but not in the tumor with [89Zr]Zr-DFO-N-suc-CSF1R-mAb most likely due to antibody-mediated depletion of intratumoral macrophages." (PMID 34976826, 2021). "Inhibitors of CSF1R, CCL2 and CCR2, CD47/SIRPα complex antagonists, CD40 agonist antibodies, and inhibitors of PI3Kγ and TREM2 protein are undergoing clinical evaluation for various tumor types." (PMID 34638378, 2021). "In addition, estrogen receptor beta (ERβ) agonist LY500307 reduced tumor-derived CSF1 and decreased infiltration of CSF1R+ MDSCs in the tumor bed." (PMID 35003065, 2021). "Acquired resistance to long-term CSF-1R inhibition was correlated with increased insulin-like growth factor (IGF-1) signaling between macrophages and tumor cells, leading to aberrant activation of phosphatidylinositol 3-kinase (PI3K) signaling, therefore promoting tumor cell survival and invasion." (PMID 34950148, 2021). "Likewise, CSF1R blockade and anti-PD1 therapy induces tumor regression in mice, but shows limited anti-tumor activity in PDAC patients with advanced disease (NCT02713529)." (PMID 34201127, 2021). "Following [89Zr]Zr-DFO-N-suc-CSF1R-mAb administration, tumor macrophages were almost absent, whereas isotype-group tumors contained over 500 cells/mm2." (PMID 34976826, 2021). "Among myeloid cell types in the tumor, monocyte-derived macrophages, defined by markers such as CD14, CSF1R and LGMN and dendritic cells were increased, while tissue-resident macrophages and monocytes were decreased, which we also observed in an independent dataset." (PMID 34663877, 2021). "Moreover, combining a CSF1R inhibitor with a CXCR2 inhibitor was shown to block granulocyte infiltration of tumors triggered by the inhibition of CSF1R and significantly reduce tumor growth." (PMID 34124076, 2021). "In fact, the sole CSF1R blockade slightly delayed tumor growth, and the PD-1 blockade induced tumor regression in some, but not all animals." (PMID 33212945, 2020). "The combination of anti-CD40 with anti-CSF-1R, which impairs the recruitment of new TAMs towards the tumor, was effective to treat “cold” preclinical tumor models, not responsive to immune checkpoint inhibitors (ICIs)." (PMID 33050070, 2020). "The majority of macrophages present in the tumor microenvironment are recruited from bone marrow-derived monocytes through the CC chemokine 2 (CCL2/CCR2) and colony stimulating factor 1 (CSF-1/CSF-1R) signaling pathways." (PMID 32326073, 2020). "In contrast, Csf1r, the gene encoding CSF1 receptor, is highly expressed in TAMs and monocytes, but not in tumor cells." (PMID 32286255, 2020). "Treatment with anti-CSF1R depletes only TAMs with an inflammatory gene signature but not PMN-MDSCs in colorectal cancer patients, leading to cancer-promoting effects through the accumulation of tumor-infiltrating PMN-MDSCs, which aggregated in tumors." (PMID 32801364, 2020). "CSF-1R is a tyrosine kinase receptor that when bound with its ligand CSF-1 promotes the differentiation and expansion of myeloid cells into MDSC and TAMs in addition to promoting their migration to tumours." (PMID 32121014, 2020). "In this study, CSF-1R was found highly expressed at the tumor boundary in patients with HCC, and also highly expressed in macrophages, but not tumor cells; making CSF-1R a feasible target." (PMID 32760707, 2020). "Nevertheless, we also note that integrin activation appeared as a universal mechanism detected in pre-activation cells of tumor core and periphery, while CD44 and NRP1/2 activity was higher in tumor core and chemokine receptors CCR1 and CSF1R were higher ranked in the tumor periphery." (PMID 33177572, 2020).